GPAA1 (glycosylphosphatidylinositol anchor attachment 1)
Diseases named in the same sentence as GPAA1 in open-access papers (continued):
Sharing a sentence is not in itself a finding about the gene and the disease.
tumor (8 papers, 2019 to 2026). "The strong association between GPAA1 expression and cold tumor phenotype suggests that GPAA1 could serve as a biomarker to identify patients less likely to respond to immune checkpoint inhibitors." (PMID 41367867, 2025). "Mechanistically, GPAA1 enhanced the levels of metastasis-associated GPI-anchored proteins to increase tumour metastasis and intensified lipid raft formation, which consequently promoted the interaction between EGFR and ERBB2 as well as downstream pro-proliferative signalling." (PMID 31118109, 2019). "A particularly significant finding of our study is the association between GPAA1 expression and genomic instability markers, including aneuploidy, HRD, and tumor ploidy." (PMID 41367867, 2025). "A comprehensive analysis utilizing the TIMER database and eight immune infiltration algorithms indicated that elevated GPAA1 expression was inversely correlated with the degree of tumor immune infiltration." (PMID 41367867, 2025). "In terms of genetic mutation characteristics, GPAA1 expression was positively correlated with aneuploidy, HRD, and tumor ploidy (p < 0.05), with these associations being particularly pronounced in CRC." (PMID 41367867, 2025). "Perhaps the most clinically relevant finding is the demonstration that GPAA1 promotes an immunosuppressive tumor microenvironment characteristic of cold tumors." (PMID 41367867, 2025). "In conclusion, our study establishes GPAA1 as a multi-functional oncogenic factor in CRC that promotes tumor progression through direct effects on tumor cell behavior, induction of genomic instability, and creation of an immunosuppressive microenvironment." (PMID 41367867, 2025). "When tumor cells high expressed GPAA1 and PIGU, the fluorescence intensity of CD8 molecules in peripheral infiltrating lymphocytes noticeably decreased, indicating a reduction in the number of CD8+ T cells." (PMID 39015576, 2024). "Some glycosylation factors showed genomic alterations (SNVs and CNVs) in 15% of tumor samples (namely GPAA1, PIGZ and B3GNT5) with a predominance of amplifications." (PMID 36009354, 2022). "Six characteristic genes (IQCE, RFX6, GPAA1, BAHCC1, CLEC2B, and AGAP2) were selected by random forest feature selection, many of which have been reported to be associated with tumor progression." (PMID 32462000, 2020). "Data mining was performed to determine the pattern of GPAA1 expression and the reason for its overexpression in tumour and adjacent normal tissues." (PMID 31118109, 2019). "Suppression of GPAA1 attenuated tumour growth in vivo, as exhibited by the tumour weight and tumour volume measurements." (PMID 31118109, 2019). "For the treatment, the research of oncogenic function indicated that GPAA1 can greatly promote tumour growth and metastasis, so destroy the effect of GPAA1 will possibly prevent tumour progression." (PMID 31118109, 2019). "GSEA results revealed that GO analysis was mainly enriched in processes such as “cellular respiration” and “generation of precursor metabolites and energy,” suggesting that GPAA1 may enhance the metabolic activity of tumor cells to promote their proliferation." (PMID 41367867, 2025). "Furthermore, by leveraging multi-algorithm immune infiltration analysis and genomic instability correlation analysis, the study explored how GPAA1 regulates the development of the cold tumor phenotype in CRC." (PMID 41367867, 2025). "Third, in vivo studies using CRC xenograft models are needed to confirm whether GPAA1 inhibition reverses the cold tumor phenotype and suppresses tumor growth." (PMID 41367867, 2025). "Therefore, we believe that targeting GPAA1-mediated synthesis of GPI-anchored proteins is a potential tumor-targeted therapeutic option." (PMID 36059802, 2022). "To identify the biological function of GPAA1 in vivo, we established a subcutaneous tumour model." (PMID 31118109, 2019). "This suggests that GPAA1 may promote tumor progression by altering the immune cell composition." (PMID 41367867, 2025).
tumor (continued). "Our multi-algorithm immune infiltration analysis revealed that high GPAA1 expression correlates with reduced infiltration of CD8+ T cells and other anti-tumor immune cells, while increasing pro-tumor M2 macrophages." (PMID 41367867, 2025). "GPAA1 expression, ERBB2 expression, age, tumour size, vascular invasion, TNM stage, lymphatic metastasis, and perineuronal invasion were significantly correlated with overall survival." (PMID 31118109, 2019). "The integrated multi-omics, single-cell, spatial transcriptomic, and in vitro functional data collectively reveal that GPAA1 acts as a pro-tumorigenic factor in CRC, offering novel insights into its role in tumor progression and immunosuppression, as well as potential clinical value." (PMID 41367867, 2025). "The positive correlation between GPAA1 expression and these markers suggests that GPAA1 may promote CRC progression by driving genomic instability, thereby accelerating tumor evolution and therapeutic resistance." (PMID 41367867, 2025). "Moreover, ENY2 and GPAA1 were expressed in multiple cell types including CAF, TEC, TAM, and/or tumor cells." (PMID 35992857, 2022). "This suggests that GPAA1 may contribute to CRC progression not only through direct effects on tumor cell behavior but also by promoting genomic instability, which could accelerate tumor evolution and therapeutic resistance." (PMID 41367867, 2025).
infection (3 papers, 2022 to 2025). The state of being infected such as from the introduction of a foreign agent such as serum, vaccine, antigenic substance or organism. "Notably, knockout of PIGA, PIGV, or GPAA1 significantly increased the infection of other coronaviruses relative to controls, with the strongest effects observed for HCoV-229E (7-fold) and PEDV (20-fold)." (PMID 40901862, 2025). "We re-introduced PIGA or GPAA1 cDNA into the respective knockout HeLa cells and found that trans-complementation not only significantly reduced infection with alphacoronaviruses HCoV-229E and PEDV but also with the SARS-CoV-2 original, Delta, Omicron BA.1 and BA.2 variants." (PMID 40901862, 2025). "Among the genes with the greatest positive effect on infection efficiency after knockout were multiple GPI biosynthesis genes: GPAA1, PIGA, PIGV, and DPM1 knockouts increased infection over 8-fold compared to control, while PIGO knockout increased infection approximately 4-fold." (PMID 40901862, 2025). "We also found that PIGT-, PIGH- or GPAA1-KO cells did not support Echo7 infection." (PMID 41252368, 2025).
neurodevelopmental disorder (1 paper, 2023). A behavioral and cognitive disorder with onset during the developmental period that involves impaired or aberrant development of intellectual, motor, or social functions. "EtNP2 is fixed by GPAA1 Gln355 and Ser51, and when the latter is mutated to leucine, it results in neurodevelopmental disorders and a reduction in GPI-APs level." (PMID 37684232, 2023).
GPAA1 also shares sentences with these, for which no sentence is quoted: Ataxia (3 papers); Friedreich ataxia (3); viral infections (2); atrial fibrillation (1); bacterial infections (1); bladder cancer (1); cardiac disease (1); cardiomyopathy (1); Cognitive impairment (1); epilepsy (1); escherichia coli infection (1); head and neck cancer (1); heart failure (1); Intellectual disability (1); legionellosis (1); leukaemias (1); lung squamous cell carcinoma (1); lymphoma (1); Nystagmus (1); oesophageal cancers (1); Osteopenia (1); peripheral sensory neuropathy (1); prostate carcinoma (1); scoliosis (1); Sensory neuropathy (1); Sepsis (1); stomach cancer (1); triple-negative breast carcinoma (1).